TMPRSS2 (transmembrane serine protease 2)
Diseases named in the same sentence as TMPRSS2 in open-access papers (continued):
Sharing a sentence is not in itself a finding about the gene and the disease.
tumor (continued). "In agreement with the mixed normal and tumor datasets, PBMC displayed positive correlations between ACE2/TMPRSS2, TMPRSS2/FURIN, ACE2/TFRC, FURIN/TFRC, TMPRSS2/CTSL, FURIN/CTSL, TMPRSS2/MYC, and FURIN/AKT1 and a negative association between ACE2/ADAM17." (PMID 33796097, 2021). "The TMPRSS2-ERG fusion is an early and one of the most common genetic abnormalities responsible for tumor invasion and progression affecting growth pathways and regulating differentiation, cell cycle, proliferation, angiogenesis and morphology in PCa." (PMID 34277455, 2021). "Taken together, these data describe tumor- and lung-pertinent expression patterns of the major SARS-CoV-2 receptor ACE2 and priming proteases TMPRSS2 and TMPRSS4 in LUAD patients." (PMID 33809063, 2021). "TMPRSS2:ERG fusion status was similar across clusters, as was predominant tumor location within the prostate gland." (PMID 32599760, 2020). "It was shown that TMPRSS2-ERG knockdown mediated by siRNA declines cell viability and inhibits tumor growth." (PMID 33287240, 2020). "AR can modulate the expression of TFs, biomarkers and vital tumour promoters in PrCa development, such as KLK2, KLK3, MYC, MSMB and TMPRSS2." (PMID 32397189, 2020). "We used tumor immune assessment resource (TIMER), Oncomine database, and GTEx project to obtain the mRNA expression level of TMPRSS2 in PRAD." (PMID 33193689, 2020). "Knockdown of TMPRSS2-ERG has been reported to inhibit cell proliferation in vitro, and knockdown of ERG reduced tumor progression in vivo in an orthotopic mouse model." (PMID 30664691, 2019). "Our data show that enzalutamide inhibited the growth of VCaP cells expressing TMPRSS2-ERG fusion genes, but when ERG factor was stably knocked down with lentiviral shERG RNA, tumor growth inhibition occurred at lesser extent." (PMID 31638934, 2019). "Then these two types of tumor tissues and their 2D and 3D cultures were investigated for changes considering methylation levels in PAX5, TMPRSS2, and SBDS genes using real-time polymerase chain reaction." (PMID 30792990, 2019). "Pooled odds ratio (ORs) with 95% confidence intervals (CIs) were calculated to estimate the correlation between TMPRSS2-ERG fusion gene and tumor features." (PMID 30459527, 2018). "New PC3M-luc TMPRSS2-ERG cells stably expressing the fusion showed increased migration ability and a higher subcutaneous tumor development." (PMID 28055969, 2017). "By way of subcutaneous injection, we clearly demonstrated that TMPRSS2-ERG overexpression leads to higher bioluminescent signal, which reflects the presence of more tumor cells." (PMID 28055969, 2017). "This may be due to the presence of micro foci of tumor in subsequent sections of the tissue extracted for RNA analysis below that originally analyzed by the pathologist and may explain why some ‘benign’ regions unexpectedly showed positive TMPRSS2:ERG expression." (PMID 27144529, 2016). "Errors in this process result in recombinogenic TMPRSS2:ERG fusion and eventually in clonal selection of tumor cells carrying this alteration." (PMID 27530104, 2016). "Since tumours with TMPRSS2-ERG fusions have an estrogen-regulated gene signature, it is also possible that re-activation of ERα expression is more common in this subset of tumours." (PMID 25436982, 2015). "The expression of AR targeted genes including PSA, TMPRSS2 and UBE2C as well as the tumor proliferation index Ki67 were more strongly inhibited by ENZ plus ICRF187." (PMID 26009876, 2015). "The abundant molecular database attached to our tumor collection further enabled us to analyze the role of HOXB13 in tumors of different molecular subtypes, the most common of which is the TMPRSS2:ERG gene fusion." (PMID 25825985, 2015). "Transcriptional upregulation of the chemokine receptor 4 gene (CXCR4) in organ-confined tumor cells that overexpress the ETS-related gene ERG (i.e., TMPRSS2-ERG fusion) increases the motility of prostate tumor cells in vitro." (PMID 25884570, 2015).
tumor (continued). "Here, we uncover a remarkably significant difference in PDE4D7 expression between TMPRSS2-ERG-negative and TMPRSS2-ERG-positive tumour samples." (PMID 26575822, 2015). "With high levels of endogenous wild type AR and TMPRSS2-ERG fusions as well as expression of many prostate epithelial markers, these cells serve as a useful model for CRPC tumor progression and metastasis." (PMID 22849360, 2012). "The absence of a linear relationship between the Gleason grade and TMPRSS2 histoscores suggests that tumor differentiation alone does not predict pulmonary TMPRSS2 expression." (PMID 41150771, 2025). "Moreover, the examination of gene expression and violin plots demonstrated a high expression of a group of AR signature genes, including KLK3, AR, TMPRSS2, NKX3.1, and AMACR across all clusters, indicating their tumor origin." (PMID 38732035, 2024). "In addition to being contiguous in space, this tumor showed homogeneous ERG expression, indicative of a TMPRSS2-ERG gene rearrangement." (PMID 37971875, 2023). "Furthermore, we also found that TMPRSS2 protein was significantly reduced in male LUAD patients and correlated with higher tumor grade." (PMID 36992839, 2023). "Another study found that high DAXX expression correlated with transmembrane protease, serine 2 (TMPRSS2)/ERG rearrangement, ERG expression, high tumor Gleason grade, advanced pT stage, high Ki-67 labeling index, and early prostate-specific antigen (PSA) recurrence." (PMID 37958340, 2023). "Due to the multifocal nature of PCa, tumor foci can be found with and without a TMPRSS2:ERG in individual prostates such that they are present in ~70% of cancerous prostates, making them a more useful biomarker than was originally apparent." (PMID 36765747, 2023). "Our data further supports this theory, with negative TMPRSS2-ERG tumor samples (TMPRSS2-ERG-) exhibiting downregulation of genes akin to those identified upon stratification by PDE4D7 score." (PMID 37752916, 2023). "A total of 103 samples from 20 PCa patients were analyzed; foci of adjacent non‐tumor prostate tissue, HGPIN, GL3, GL4, GL5, and LN were examined to determine the presence of the TMPRSS2‐ERG fusion and ERG, EZH2, NKX3.1, and SPINK‐1 expression levels, using RT‐PCR." (PMID 36199157, 2023). "Even though TMPRSS2‐ETS gene fusion is not a tumor progression marker but due to its relevance with aggressiveness, TMPRSS2‐ETS gene fusion remains a curious novel target for therapeutic development in PCa." (PMID 38089408, 2023). "Considering the pathological role of the TMPRSS2/ERG fusion gene, this function of Efp could seem to be tumor suppressive." (PMID 35954308, 2022). "Although CXCL10 shows no evident interconnection with TMPRSS2 in the PPI network, in PRAD patients, it has been linked to a group of tumor associated macrophages (TAMs) which are further classified into two different subtypes, M1 and M2." (PMID 36239108, 2022). "Furthermore, we found inversions with BND interrupting TMPRSS2 and ERG genes in three tumours from European patients and one RNA-seq validated tumour from the African patient UP2103." (PMID 36045381, 2022). "Studies have shown that regardless of the size of the primary tumor, deletion of TMPRSS2 in tumor-bearing mice can significantly reduce metastasis." (PMID 35281819, 2022). "Investigation of gene fusions caused by SVs identified; the well-established PCa fusion gene TMPRSS2-ERG in 10% and 33% of tumours from African and European patients, respectively; the previously reported African-specific ZBTB20-LSAMP; and nine novel African-associated fusions." (PMID 36045381, 2022). "Moreover, the DNA methylation level of TMPRSS2 was also greatly upregulated in LUAD and LUSC patients with different sexes, tumor stages, nodal metastasis statuses, ages and races." (PMID 35017320, 2022). "In addition, multiple datasets showed that patients with up‐regulated TMPRSS2 expression had significantly bad OS, RFS and DMFS in patients with most tumour types." (PMID 34951103, 2022).
tumor (continued). "The high expression levels of RAB7A, PIK3C3, ATP6AP1, ATP6V1A, CCDC22, and NPC1 were significantly associated with lower tumor purity of patients with hematologic cancer LAML, while TMPRSS2, PIK3C3, ATP6AP1, and ATP6V1A expressions were obviously correlated with higher tumor purity of KICH patients." (PMID 35082790, 2021). "Altogether, these data suggest that TMPRSS2, with its high expression and usage of TMPRSS2‐001 and TMPRSS2‐201 containing both SRCR_2 and Trypsin (Tryp_SPc) in PRAD, should play important roles in tumorigenesis and COVID‐19 viral entry into PRAD tumour tissues." (PMID 33609069, 2021). "Despite the lack of significant association of the unfavorable prognosis and presence of the TMPRSS2–ERG fusion transcript, comprehension of the TMPRSS2–ERG fusion transcript status in tumor is important to clarify which PCa prognostic model is appropriate for application." (PMID 34205581, 2021). "The second principal component, PC2, explains 12% of the variation and demonstrates separation of tumor samples with TMPRSS2 fusion (blue markers) from those without TMPRSS2 fusion (yellow-red markers)." (PMID 33963293, 2021). "We also analyzed the expression of ACE2 and TMPRSS2 in non-epithelial cells (i.e., immune cells, endothelial cells, and fibroblasts) from human normal and tumor colorectal tissues." (PMID 33479506, 2021). "This TMPRSS2-ERG positive tumour had a high PGA (10.2%), but lacked any known deleterious somatic mutation." (PMID 32392735, 2020). "Using the TMPRSS2:ERG fusion as a putative early driver of tumorigenesis, based on its expression in all right-sided tumor foci (B2, B3, R2, and R3), we modeled that the IDC-P and invasive foci identified in the RP descended from IDC-P and invasive foci sampled on biopsy." (PMID 32054861, 2020). "However, TMPRSS2 exhibited very low expression levels, and also negatively correlated with tumor stages in KIRP tumor tissues along with ANPEP (ρ = −0.153, p < 0.05)." (PMID 33330620, 2020). "Confirming our findings, TMPRSS2 expression was significantly reduced in tumor samples compared to non-tumorous tissues." (PMID 32967703, 2020). "We compared the TMPRSS2 promoter methylation in tumor versus non-tumorous tissues in HNSCC TCGA dataset." (PMID 32967703, 2020). "We observed a clear difference in BCR progression, free survival analysis between the fusion positive vs. negative tumours with a highly significant logrank p (<0.0001) for the PDE4D7 categories in the presence of the rearranged TMPRSS2-ERG gene fusion." (PMID 31275657, 2019). "The rationale for this added prognostic benefit of PDE4D5 and PDE4D9 is supported by the differences in prediction power between TMPRSS2-ERG positive vs. gene fusion negative patient tumours." (PMID 31275657, 2019). "The primary objective of our study is to determine whether primary tumor tissue and cultured tumor cells in 2D and 3D tissue culture systems have the same methylation signature for PAX5, TMPRSS2, and SBDS." (PMID 30792990, 2019). "We then tested an available pharmacological sGC inhibitor on treating TMPRSS2-ERG-positive xenograft tumors and showed that inhibitor treatment alone or in combination with enzalutamide (an AR antagonist) can significantly suppress PCa tumor growth." (PMID 30718921, 2019). "We observed a similar result to this for the PDE4D9 score categories with a logrank p<0.0001 in survival analysis in TMPRSS2-ERG negative tumours." (PMID 31275657, 2019). "First, we showed that the TMPRSS2-ERG fusion increases cell migration and subcutaneous tumor size." (PMID 28055969, 2017). "The remaining eight are known fusion transcripts (e.g. TMPRSS2-ERG, C9orf163-SEC16A, SMG5-TMEM79, and KLK4-KLK3), of which TMPRSS2-ERG is the most common, and was found to be positive in 19 (45%) of the 44 primary tumor samples." (PMID 28467780, 2017).
tumor (continued). "Furthermore, double rearrangements of ERG with TMPRSS2 and SLC45A3 or NDRG1, well known androgen-induced genes, have been found to coexist in the same tumor in a subset of PrCa cases." (PMID 29088771, 2017). "RNAseq analyses in both centers identified fusion transcripts including a common rearrangement between TMPRSS2 and ERG in one tumor, though the detection of other fusion transcripts varied substantially depending on the algorithm used to identify such transcripts." (PMID 27167109, 2016). "When the NPs siRNA TMPRSS2-ERG-SQ were injected by i. v. in SCID mice, tumour growth was strikingly inhibited (70%, p<0.001) compared to mice treated with NPs siRNA Control-SQ, non-vectorized siRNA TMPRSS2-ERG IV or saline solution." (PMID 25933120, 2015). "Interestingly, when mice bearing prostate VCaP xenografted cells were treated with NPs siRNA TMPRSS2-ERG IV-SQ, the tumour growth was strikingly inhibited as early as the first week of treatment." (PMID 25933120, 2015). "Moreover, Ki67 proliferation marker was also decreased in tumours treated with NPs siRNA TMPRSS2-ERG IV-SQ, indicating a reduction of mitotic index by vectorized siRNA TMPRSS2-ERG treatment." (PMID 25933120, 2015). "Borno and co-workers however, also identified a miRNA-dependent mechanism for EZH2 overexpression in TMPRSS2:ERG negative tumours." (PMID 25496077, 2014). "Additionally, androgen treatment can initiate TMPRSS2-ERG fusion in both prostate normal and tumor cells." (PMID 24739220, 2014). "Potentially the response to ADT could also be followed, assuming that regression of the tumour resulted in less/no expression of the biomarkers, but the loss of expression could also be because of the reduced expression of androgen-responsive genes, like TMPRSS2 and PCA3." (PMID 19401683, 2009). "Using a nested PCR-based approach, we were able to show that tumour exosomes carry genetic information specific for PCa, and as a proof-of-principle we used tumour exosomes to detect two PCa mRNA biomarkers, PCA-3 and TMPRSS2:ERG." (PMID 19401683, 2009). "Attard and colleagues (2007) suggest that the sequence intervening the TMPRSS2 and ERG genes may contain tumor-suppressor genes which when lost, increase disease aggressiveness." (PMID 18694509, 2008). "If plant miRNAs repress TMPRSS2 expression, they could potentially reduce fusion formation and tumor progression without affecting healthy tissues." (PMID 41440174, 2025). "TMPRSS2:ERG is an AR regulatory gene that is restored in CRPC and may promote tumor progression." (PMID 38887275, 2024). "In addition, the expression of TMPRSS2 was much higher in tumor cells of UCEC than that in normal samples (p = 2.3E-16) and the high expression of TMPRSS2 might suggest a favorable prognosis in UCEC (p = 0.029)." (PMID 33061814, 2020). "In addition, the processes of tumor evolution are also different between fusion positive and negative tumors, with TMPRSS2-ERG tumors characterized by chromoplexy, while chromothripsis is more common in TMPRSS2-ERG negative tumors." (PMID 32341752, 2020). "This is the first genetic epidemiological study on the association of genetic variants at a genome-wide scale, as opposed to selected SNPs, with TMPRSS2: ERG fusion status both by index tumor or by any tumor foci, considering the multifocal and multiclonal nature of the disease." (PMID 32341752, 2020). "For this purpose, our first aim was to cultivate the tumor cells in 2D and 3D tissue culture systems and to determine whether the primary tumor tissue and cultured cells in 2D and 3D tissue culture systems had the same methylation signature for PAX5, TMPRSS2, and SBDS." (PMID 30792990, 2019). "TMPRSS2 and SLC45A3 rearrangements may coexist in the same tumor." (PMID 29088771, 2017). "In addition to tumor architecture, differences in clinical and epidemiological characteristics have also been investigated for TMPRSS2:ERG positive and negative PrCa." (PMID 27798103, 2016).